POLE (DNA polymerase epsilon, catalytic subunit)
Diseases named in the same sentence as POLE in open-access papers (continued):
Sharing a sentence is not in itself a finding about the gene and the disease.
glioblastoma (continued). "Here, an increased density of total CD3+ T lymphocytes and/or CD4+ or CD8+ subsets in spatial patterns suggesting interaction with the tumor microenvironment was observed in eight of nine (89%) POLE-mutated primary glioblastomas or spinal metastases compared to POLE WT controls." (PMID 37990341, 2023). "Additionally, germline variants in POLD1, located at 19q13.33, were detected in 2/34 (6%) patients with 1p/19q-codeleted oligodendrogliomas, while POLE variants were identified in 2/4 (50%) glioblastoma patients with a spinal metastasis." (PMID 37990341, 2023). "Taken together, in eight of nine (89%) POLE-mutated primary glioblastomas or spinal metastases, including three tumors harboring variants classified as likely pathogenic, the density of total CD3+ T lymphocytes and/or CD4+ or CD8+ subsets was increased compared to controls with WT POLE." (PMID 37990341, 2023). "With growing real-world evidence, we propose that ICI may be considered among the treatment options for recurrent hypermutated glioblastoma with POLE mutation." (PMID 34345822, 2021). "While waiting for more trial results, current real-world evidence, albeit limited due to its rarity, may suggest that ICI can be considered among salvage therapies for POLE-mutated recurrent glioblastoma." (PMID 34345822, 2021). "Multicolor FISH analysis of LN-229 glioblastoma cells revealed a hyperdiploid karyotype with more than two copies of the long arms of chromosome 12 harboring the POLE gene at 12q24.33 and possibly of chromosome 19 harboring the POLD1 gene at 19q13.33." (PMID 37990341, 2023). "Taken together, the viability of LN-229 glioblastoma and MMR-deficient HCT116 cells carrying CRISPR/Cas9-mediated POLE or POLD1 variants was markedly reduced." (PMID 37990341, 2023). "The density of total CD3+ T lymphocytes and/or CD4+ or CD8+ subsets was increased in six of seven (86%) POLE-mutated primary glioblastomas, and that of CD68+ macrophages in three of seven (43%) POLE-mutated primary glioblastomas compared to the mean density in five POLE WT glioblastomas." (PMID 37990341, 2023). "The siblings both had biallelic MMR disorder and so completely lacked MMR, with whole exome sequencing showing that the glioblastoma tumors had acquired spontaneous pathogenic mutations in POLE." (PMID 37388540, 2023). "Similarly, around 25% of glioblastoma patients with rare POLE/POLD1 germline variants compiled here were affected by giant cell glioblastoma, although this tumor type typically accounts for < 1% of all glioblastomas." (PMID 37990341, 2023). "The immune cell infiltrate of seven primary glioblastomas and two spinal metastases from seven patients with rare POLE variants as determined by multiplexed fluorescence IHC of immune cell markers CD3, CD4, CD8, CD68, and PD-1 was compared to that in POLE WT glioblastomas." (PMID 37990341, 2023). "In DNA of both glioblastoma and spinal metastasis of patient M2 (DNA from non-neoplastic tissue was not available), we identified the rare POLE:c.6763A>T p.(I2255F) variant that was predicted to be deleterious." (PMID 37990341, 2023). "At 10 h after BrdU treatment, the relative subpopulation of mid-S phase BrdU-positive cells was significantly increased in POLE KO versus WT cells (two-tailed Student’s t test, p = 0.0073), suggesting delayed S phase progression in POLE KO LN-229 glioblastoma cells." (PMID 37990341, 2023). "In LN-229 glioblastoma cells, genotyping of the CRISPR/Cas9-edited cells revealed 1/48 (2%) cell clones harboring a mutant POLE allele, 1/48 (2%) cell clones devoid of WT POLE alleles, 20/85 (24%) cell clones harboring a mutant POLD1 allele, and 0/85 cell clones devoid of WT POLD1 alleles." (PMID 37990341, 2023). "Furthermore, delayed S phase progression was detected in the POLE knockout LN-229 glioblastoma clone indicative of impaired polymerase function." (PMID 37990341, 2023).
glioblastoma (continued). "No glioblastomas in this large prospective cohort had POLE proofreading domain mutations occurring in isolation without accompanying mismatch repair deficiency." (PMID 38079020, 2023). "1,2 Our case here along with prior reports timely confirmed that this observation also extended to include glioblastoma and may support the use of ICI in hypermutated glioblastoma with POLE mutation." (PMID 34345822, 2021). "Therefore, to exclude a germline origin for the POLE variants detected in the glioblastoma, the Case 1 patient’s PBL genomic DNA was sequenced but no POLE or POLD1 variants were detected." (PMID 38789506, 2024). "As deficiency of POLE, the catalytic subunit of the major leading-strand DNA polymerase ε, is expected to impact DNA replication, we performed flow cytometry-based cell cycle analysis of BrdU pulse-labeled and 7-AAD-stained POLE WT and KO LN-229 glioblastoma cells." (PMID 37990341, 2023). "Furthermore, non-benign POLE and POLD1 variants were identified in tumor DNA of 5.3% (POLE) or 2.5% (POLD1) glioblastomas." (PMID 37990341, 2023). "No underlying differences in patient sex, age at diagnosis, tumor location, presence/absence of POLE mutation, or somatic versus germline origin of mismatch repair gene mutation were appreciable between the two DNA methylation clusters of de novo RRD glioblastomas." (PMID 38079020, 2023).
uterine cancer (10 papers, 2017 to 2024). Primary or metastatic malignant neoplasm involving the uterine corpus and/or the cervix. "A total of 945 samples, notably colorectal and uterine cancers, were hypermutated, either as result of defective mismatch repair (dMMR) or POLE mutation." (PMID 38890488, 2024). "They build upon and expand the previously well documented good prognostic impact of POLE exonuclease mutations in uterine cancer, that have generated intense interest in part due to the paradox of a favorable prognosis in tumors with pathologic indicators of poor prognosis." (PMID 32838755, 2020). "Most studies focus on intestinal and uterine cancers with POLE mutations." (PMID 32838755, 2020). "The OCAv3 NGS assay offers a more time-, cost- and tissue-efficient method for simultaneously assessing POLE mutations and ERBB2 amplifications in uterine carcinomas, particularly in cases with limited tissue material." (PMID 39682116, 2024). "Since mutations in POLE confer increased disease free survival (DFS) in patients with uterine cancer, even in those patients with high-grade tumors, we investigated the prognostic role of POLQ and REV3L mutations in POLE mutant tumors." (PMID 32838755, 2020).
lung carcinoma (9 papers, 2018 to 2025). "For example, the frequency and type of POLE mutations vary among different lung cancer types, and their relationship with other gene mutations and clinical features is not fully understood." (PMID 40583191, 2025). "In a study of the Chinese population, P286R and F699Vfs*11 were identified as the hotspot mutations of POLE in lung cancer, whereas the hotspot mutations recorded in the COSMIC database are P286R and V411L." (PMID 35780178, 2022). "Additionally, we noted tentative associations with higher mutation burden cancer types, including MSI, POLE-mutant, and lung cancers." (PMID 41023738, 2025). "In recent years, POLE as a potential target for the treatment of lung cancer has attracted more and more attention." (PMID 40583191, 2025). "In pharmacogenomic screens of 108 lung cancer cell lines, we identified anticancer drugs responsive to cell lines with low POLE expression." (PMID 32433714, 2020). "Using the Genomics of Drug Sensitivity in Cancer (GDSC) and the Catalogue Of Somatic Mutations In Cancer (COSMIC) databases, we performed high-throughput drug sensitivity screening in lung cancer cell lines according to POLE expression." (PMID 32433714, 2020). "Early studies identified associations with lung cancer risk in selected mutated NER genes (ERCC1-6, LIG1, POLE, XPA, and XPC genes)." (PMID 30181806, 2018). "Although the exact causal relationships of these mechanisms require further investigation, the potential link between POLE and key oncogenic pathways underscores its important role in tumorigenesis and offers new therapeutic targets and strategies for lung cancer and other malignancies." (PMID 40583191, 2025). "Therefore, more large‐scale clinical trials and in‐depth research are needed in the future to further validate the effectiveness and safety of POLE as a therapeutic target for lung cancer." (PMID 40583191, 2025). "However, the significance of MMR mutations in lung cancer has not been well characterized, and the relevance of other processes, including homologous recombination (HR) and polymerase epsilon (POLE) activity, remains unclear." (PMID 30824826, 2019).
lymph node metastasis (9 papers, 2019 to 2025). "These significant findings (p≤0.001) demonstrate the protective effect of POLE mutation against lymph node metastases." (PMID 35139130, 2022). "In detail, EC patients with a pathogenetic variant in the POLE exonuclease region were predominantly characterized by early-stage, high-grade, endometrioid histotypes, as well as the absence of lymph node metastasis." (PMID 36358847, 2022). "POLE mutations significantly protected against lymph node metastases (OR = 0.202, p = 0.001), and have no clear association with lymph-vascular space invasion (OR = 0.967, 95% 0.713–1.310, p = 0.826)." (PMID 35139130, 2022). "In our cohort, POLE-mutated tumours do proceed to lymph-node metastasis and may also be non-endometrioid." (PMID 30917185, 2019).
pancreatic cancer (8 papers, 2014 to 2024). "In other solid tumors such as pancreatic cancer, mutations in the hotspot regions of POLE are very rare events." (PMID 39239272, 2024). "One highly mutated sample with a POLE mutation was observed in breast and pancreatic cancers; the POLE-mutated sample was the most highly mutated in each site." (PMID 28870239, 2017). "In advanced pancreatic cancer, it is highly unlikely that POLE mutations contribute to genetic instability; therefore, POLE mutations do not serve as a relevant biomarker and should not be tested for on a regular basis." (PMID 39239272, 2024). "Furthermore, as observed for other tumor types, pathogenic mutations affecting POLE also seem to be associated with a very high-TMB, defined as hyper-ultra-mutated phenotype in pancreatic cancer." (PMID 34206554, 2021).
carcinosarcoma (7 papers, 2020 to 2025). A malignant tumor composed of a mixture of carcinomatous and sarcomatous elements. "Following TCGA, studies have demonstrated that POLE mutations can also occur in undifferentiated/dedifferentiated carcinomas, carcinosarcomas, and clear cell carcinomas." (PMID 41514564, 2025). "POLEmut carcinosarcomas have been described in the literature, but all reports were published before the definition of pathogenic POLE mutations in early 2020 by Leon-Castillo et al12." (PMID 38303106, 2024). "POLE mutations are more frequent in high-grade ECs (12.1%) than in low-grade ECs (6.2%) and occur in 12.4% of undifferentiated/dedifferentiated, 3.8% of clear, and 5.3% of carcinosarcomas." (PMID 41312167, 2025). "Endometrial lymphoepithelioma-like carcinoma with carcinosarcoma was classified as POLE mut and IAm-POLE mut by the WHO molecular classification and 2003 FIGO staging system, respectively." (PMID 40761799, 2025). "Our SNV/INDEL results revealed POLE mutations (c.1376C>T p.S459F) occurring at frequencies of 18.53% and 42.8% in LELC and carcinosarcoma, respectively." (PMID 40761799, 2025).
colorectal polyps (7 papers, 2015 to 2025). "Germline mutations in POLE and POLD1 have been shown to predispose patients to multiple colorectal polyps and a wide range of neoplasms." (PMID 34868924, 2021). "To discover the underlying genetic causes of multiple colorectal polyps and CRC in genetically unexplained cases, we aimed to screen the exonuclease domains of POLE and POLD1 in this group of patients." (PMID 30827058, 2019). "Here, we screened the exonuclease domain of POLE and POLD1 to detect causative variants in 332 index patients with multiple colorectal polyps." (PMID 30827058, 2019). "Pathogenic mutations involving the proofreading domains of POLE and POLD1 are widely known to be associated with colorectal polyposis and cancer." (PMID 31866764, 2019). "We recommend that screenings of POLE and POLD1 should still be considered, although pathogenic variants in POLE and POLD1 probably occur at a low frequency in patients with multiple colorectal polyps." (PMID 30827058, 2019). "While predisposing variants in genes such as NTHL1, MSH3, POLE, POLD1, DSC2, and PIEZO1 have been associated with colorectal polyposis, they do not fully mimic the classical FAP phenotype." (PMID 41204315, 2025). "Using a custom next‐generation sequencing panel, we sequenced the exonuclease domains of POLE and POLD1 in 332 index patients diagnosed with multiple colorectal polyps without germline alteration in colorectal polyposis predisposing genes." (PMID 30827058, 2019).
cutaneous melanoma (7 papers, 2017 to 2022). A primary melanoma arising from atypical melanocytes in the skin. "SBS7 and SBS10 were the most frequent signatures, mostly found for skin melanomas and POLE-mutated hypermutated genomes, respectively." (PMID 35902761, 2022). "POLE2 is a subunit of the polymerase epsilon enzyme complex; we have previously demonstrated that a deleterious variant in another member of this complex, POLE, was associated with cutaneous melanoma development." (PMID 29641532, 2018). "In the cutaneous melanoma PanCancer Atlas study (provisional), 11 of 27 samples (40.7%) with CTCFL mutations had lesions in one of the four MSI associated genes or the POLE or POLD1 genes." (PMID 30275357, 2018).
IMAGe syndrome (7 papers, 2020 to 2023). IMAGe syndrome is characterized by the association of intrauterine growth retardation, metaphyseal dysplasia (and short limbs), adrenal hypoplasia congenita, and genital anomalies. "Genetic ablation of Pole4 in mice leads to a multifaceted disorder characterized by reduced growth, developmental abnormalities, lymphopenia, and increased lymphomagenesis, which resembles IMAGe syndrome in patients affected by hypomorphic mutations of POLE." (PMID 35649380, 2022). "Interestingly, CALMs were reported in one-third of biallelic POLE mutation carriers with IMAGe syndrome (intrauterine growth restriction, metaphyseal dysplasia, adrenal hyopoplasia congenita, and genital anomalies; MIM 618336)." (PMID 35158896, 2022). "Notably, patients with hypomorphic mutation of POLE, in FILS and IMAGe syndromes, and POLE2 exhibit a characteristic reduction in the number of B lymphocytes and variable degrees of immunodeficiency." (PMID 35649380, 2022).
Immunodeficiency (7 papers, 2015 to 2025). Failure of the immune system to protect the body adequately from infection, due to the absence or insufficiency of some component process or substance. "FILS syndrome (MIM# 615139), a very rare recessive Mendelian disorder characterized by facial dysmorphism, immunodeficiency, livedo, short stature, and variable skin manifestations, is caused by POLE pathogenic variants located outside the exonuclease domain and/or disrupting the encoded protein." (PMID 37848928, 2023). "Finally, mutations in genes encoding subunits of the replicative DNA polymerases POLA1, POLD1, POLD2, POLE, and POLE2 have implicated components of the active replisome in primordial dwarfism, often with immune deficiency, and in the case of POLE, adrenal failure." (PMID 33060134, 2020). "Biallelic POLE pathogenic variants have also been associated with another rare Mendelian syndrome, IMAGE-I (MIM# 618336), characterized by intrauterine growth retardation, metaphyseal dysplasia, adrenal hypoplasia congenita, genital anomalies, immunodeficiency, and diffuse large B-cell lymphoma." (PMID 37848928, 2023).
stomach cancer (7 papers, 2017 to 2023). "Stratified by cancer types, POLE exonuclease domain mutations occurred in 7/15 colorectal, 18/26 endometrial and 6/16 stomach tumors, demonstrating cancer type specific frequencies." (PMID 32838755, 2020). "A CRC and a lymphoid neoplasm harboring POLD1 p.Arg352Cys, as well as a stomach carcinoma with POLD1 p.Arg525Trp, displayed hypermutation but not the POLE/D1 ED-associated signatures." (PMID 32792570, 2020).
uterine corpus endometrial carcinoma (7 papers, 2018 to 2025). A endometrial carcinoma (disease) that involves the body of uterus. "In our study, we found the POLE p.P286R (c.857C>G) mutation to be significantly associated with signature 10 in uterine corpus endometrial carcinoma." (PMID 30412573, 2018). "Similarly, uterine corpus endometrial carcinoma with genomic instability defined by high copy-number alterations, POLE mutations, and microsatellite instability had higher repstress score compared with low copy-number altered tumors." (PMID 36381660, 2022). "The most conspicuous hypermutation group existed in TCGA’s uterine corpus endometrial carcinoma (UCEC) cohort, which seemed to be predominated by subjects having both mutated DNA mismatch repair genes and mutated POLE." (PMID 35053577, 2022). "Colon adenocarcinoma and uterine corpus endometrial carcinoma showed variability in the presence or absence of microsatellite instability or hypermutation caused by POLE mutations (see alignment with corresponding mutational signatures)." (PMID 38200255, 2024). "There were statistically significant differences in immune response among these four uterine corpus endometrial carcinoma (UCEC) subtypes (P = 0.0001), in which the POLE (DNA polymerase epsilon) cases had the highest immune response and this observation is consistent with a previous report." (PMID 31645905, 2019).
hereditary cancer (6 papers, 2014 to 2025). Malignant neoplasms occurring in families at a rate greater than that expected by chance and caused by germline mutations in a specific gene. "Despite data on long-term outcomes in germline mutation carriers are still limited, however, some evidence supports the integration of the routine POLE mutation testing in EC patients, especially useful for stratifying treatment and managing familial cancer risk." (PMID 40936703, 2025). "The tumor spectrum and prevalence of POLE and POLD1 variants in hereditary cancer are evaluated in this study." (PMID 32792570, 2020). "The frequency of rare ED missense variants—including pathogenic and VUS—in POLE and POLD1 in hereditary cancer was 0.39% (9/2309)." (PMID 32792570, 2020). "POLE and POLD1 were sequenced in 2813 unrelated probands referred for genetic counseling (2309 hereditary cancer patients subjected to a multigene panel, and 504 patients selected based on phenotypic characteristics)." (PMID 32792570, 2020). "POLE c.1138G>T (p.Gly380Cys) (MAFgnomAD_NFE = 0.005%), predicted deleterious, was identified in a woman diagnosed with two synchronic breast tumors, and in an unrelated individual with multiple adenomatous polyps and no familial cancer history." (PMID 32792570, 2020).
lung adenocarcinoma (6 papers, 2018 to 2025). A carcinoma that arises from the lung and is characterized by the presence of malignant glandular epithelial cells. "Further analysis of the lung adenocarcinoma population showed that patients with both PD-L1 overexpression and POLE mutation have significantly better OS." (PMID 35780178, 2022). "Somatic mutations of multiple MMR genes as well as POLE, POLQ, ATM, and ATR were significantly associated with higher neoantigen loads in UCEC, BRCA, lung adenocarcinoma (LUAD), and STAD (FDR < 1.2 × 10−5)." (PMID 34095878, 2021).